PCSK1 (proprotein convertase subtilisin/kexin type 1)
Description:
Involved in the processing of hormone and other protein precursors at sites comprised of pairs of basic amino acid residues. Substrates include POMC, renin, oxytocin, vasopressin, enkephalin, dynorphin, somatostatin, insulin and AGRP.
Synonyms: PC1; NEC1; PC3; SPC3; PC1/3; BMIQ12
Tractability: Small molecule: a high-quality ligand is known. Antibody: UniProt predicts a signal peptide or a membrane-spanning region. PROTAC: a small molecule that binds it is known.
Target class: Enzyme; Serine protease S8B subfamily; Serine protease SB clan; Protease; Serine protease
Gene: Protein-coding gene on chromosome 5 (96,390,333 to 96,434,143, reverse strand). Ensembl gene ENSG00000175426.
Subcellular location: Cytoplasmic vesicle, secretory vesicle
Pathways (Reactome):
Metabolism of proteins: Insulin processing; Peptide hormone biosynthesis; Synthesis, secretion, and deacylation of Ghrelin; Synthesis, secretion, and inactivation of Glucagon-like Peptide-1 (GLP-1); Synthesis, secretion, and inactivation of Glucose-dependent Insulinotropic Polypeptide (GIP)
Gene Ontology:
Molecular function: serine-type endopeptidase activity; endopeptidase activity; identical protein binding; serine-type peptidase activity
Biological process: cell-cell signaling; peptide biosynthetic process; peptide hormone processing; proteolysis; insulin processing; protein processing
Cellular component: extracellular region; membrane; neuron projection; secretory granule lumen; secretory granule; transport vesicle
Genetic constraint (gnomAD): Loss-of-function variants: 39 observed, 71.88 expected, observed/expected ratio (o/e) 0.54, 90% interval 0.42 to 0.71. The upper end of that interval is the gene's LOEUF score, 0.71, which puts it in group 2 of 6, group 1 being the genes least tolerant of losing a copy. Missense variants: 660 observed, 825.04 expected, observed/expected ratio (o/e) 0.8, 90% interval 0.75 to 0.85. Synonymous variants: 315 observed, 314.34 expected, observed/expected ratio (o/e) 1, 90% interval 0.91 to 1.1.
Homologues: Orthologues: chimpanzee PCSK1 (99% identical), macaque PCSK1 (98% identical), pig PCSK1 (97% identical), dog PCSK1 (96% identical), guinea pig PCSK1 (95% identical), rabbit PCSK1 (94% identical), rat Pcsk1 (93% identical), mouse Pcsk1 (93% identical), tropical clawed frog pcsk1 (74% identical), zebrafish pcsk1 (73% identical). Paralogues in human: FURIN (42% identical), PCSK6 (41% identical), PCSK5 (40% identical), PCSK4 (38% identical), PCSK2 (37% identical), PCSK7 (33% identical), MBTPS1 (16% identical), TPP2 (16% identical), PCSK9 (13% identical).
Diseases named in the same sentence as PCSK1 in open-access papers:
PCSK1 is named in the same sentence as 201 diseases in open-access papers, as found by Europe PMC text mining. Sharing a sentence is not in itself a finding about the gene and the disease. The quoted sentences say what the papers report.
Obesity (154 papers, 2009 to 2026). Accumulation of substantial excess body fat. "Accordingly, targeted pharmacological therapies, such as metreleptin for patients carrying biallelic LEP variants and setmelanotide for patients with biallelic LEPR, POMC, and PCSK1 variants, are available for selected monogenic obesity forms." (PMID 41489710, 2026). "While mono-allelic variants in PCSK1 have been considered obesity-causing before, recent research questions the monogenic effect of heterozygous PCSK1 variants on obesity, prompting us to assess these cases conservatively." (PMID 40523925, 2025). "This narrative review examined the functional and clinical significance of UCP3 and PCSK1 variants in severe obesity, presenting two case reports to illustrate their potential impact." (PMID 40281302, 2025). "Mutations in PCSK1 have been associated with monogenic forms of obesity and endocrine disorders, including congenital proprotein convertase 1 deficiency, characterized by early-onset obesity, hypoglycemia, and malabsorptive diarrhea." (PMID 40281302, 2025). "This review aimed to explore the emerging role of rare genetic variants in UCP3 and PCSK1 in non-syndromic obesity." (PMID 40281302, 2025). "Our review highlights the potential clinical relevance of rare, functionally significant variants in UCP3 and PCSK1 in patients with severe obesity." (PMID 40281302, 2025). "Although UCP3 and PCSK1 have been extensively studied, the phenotypic impact of their combined variants on obesity remains less explored." (PMID 40281302, 2025). "We recommend that functional validation and exploring variant-variant interactions within relevant genes such as UCP3 and PCSK1 will be critical to improving our understanding of monogenic (rare) obesity and refining personalized treatment strategies." (PMID 40281302, 2025). "Mutations or polymorphisms of PCSK1 have been reported both in monogenic and polygenic forms of obesity." (PMID 39876968, 2024). "NEC1 affects several PCs, AF, and HF, and is a druggable protein that processes hormones such as insulin and its encoding gene PCSK1 associated with HF risk factors such as obesity and abnormal glucose homeostasis." (PMID 39434187, 2024). "Our study successfully identified PCSK1, a known monogenic obesity gene, in 4 patients who experienced less weight loss after surgery, thereby confirming the validity of our method." (PMID 38469147, 2024). "BPA increases the number of adipocytes by regulating the expression of the FABP4, CD36, and PCSK1 genes; decreases the release of adiponectin and other adipokines; and disrupts adipocyte metabolism, thus increasing the risk of developing obesity." (PMID 39519574, 2024). "We confirmed the efficacy of the method by identifying a mutation in known monogenic obesity gene, PCSK1, which resulted in less weight loss after surgery." (PMID 38469147, 2024). "Proprotein Convertase Subtilisin/Kexin Type 1 (PCSK1 or PC1/3) has been associated with obesity, body mass index, birth weight, and proinsulin levels." (PMID 37954272, 2023). "Regarding metabolic diseases, in this study, we analyzed the individual associations of six SNPs with obesity and metabolic syndrome, among which the G rs6235 allele of PCSK1 was associated with obesity." (PMID 37761915, 2023). "In fact, the PCSK1 SNP is the third most important gene associated with obesity; this gene is one of the first genes recognized as a monogenic cause of obesity." (PMID 37761915, 2023). "Disruption of POMC and the enzyme that cleaves POMC, prohormone convertase 1 (PCSK1), also causes severe obesity with hypopigmentation (due to the loss of MC1R signalling) and cortisol deficiency (due to a lack of ACTH)." (PMID 37661743, 2023). "A comparison between 532 non-obese French young adults and 505 obese French children showed an association between PCSK1 rs6232 (OR: 1.57, p: 0.009) and rs6235 (OR: 1.50 (1.23, p: 0.00003) and obesity, results consistent with this study." (PMID 37761915, 2023).
Obesity (continued). "PCSK1 is a member of the chymotrypsin-like preprotein convertase family and associated with obesity and diabetes, while the family is involved in the regulation of immune cells in the tumor immune response." (PMID 37180113, 2023). "Rare mutations in PCSK1 are known to cause monogenic obesity—here, a relatively symmetric pattern of increased GFAT, VAT (beta = 0.87; p = 4.1 × 10−4), and ASAT (beta = 1.04; p = 3.1 × 10−5) were observed in sex-combined analyses 66,67." (PMID 35773277, 2022). "Various human genetics studies have associated PCSK1 with metabolic phenotypes such as early onset obesity, intestinal malabsorption, gastrointestinal complications, diabetes, and reactive hypoglycemia." (PMID 36532520, 2022). "The association of obesity with rare homozygous or compound heterozygous PCSK1 variants is well established through PC1/3 deficiency and goes back as far as 1997." (PMID 36292633, 2022). "So far deficiency of PCSK1 gene and its coded protein (enzyme) activity has been confirmed in Prader–Willi Syndrome disease and associated obesity." (PMID 35621394, 2022). "As genetic diagnosis of patients can have a profound impact on tailored treatment options and care, we urge that at present, all rare heterozygous PCSK1 variants should be carefully and individually assessed before genetic obesity diagnosis." (PMID 36292633, 2022). "Seven additional publications, including rare heterozygous PCSK1 variants in the context of obesity, are incorporated in the discussion section." (PMID 36292633, 2022). "Regarding the possible involvement of (other) rare heterozygous PCSK1 variants in obesity, to date, only one heterozygous PCSK1 variant (p.Arg80*, Grch38.p13 NM_000439.5:c.238C>T) was reported to co-segregate with obesity." (PMID 36292633, 2022). "Our results also support the association between SNPs in PCSK1 with obesity and obesity-related hypertension in the young; thus, the potential neuroendocrine involvement in obesity-related hypertension development in these patients." (PMID 36010152, 2022). "More recently, a study to which we contributed implied that rare heterozygous PCSK1 variants also significantly contribute to human obesity." (PMID 36292633, 2022). "The convertase subtilisin/kexin family 1 gene (PCSK1) has been associated in various human genetics studies with a wide spectrum of metabolic phenotypes, including early-onset obesity, hyperphagia, diabetes insipidus, and others." (PMID 34996527, 2022). "Undoubtedly, more research is necessary to further elucidate the full extent to which (rare) heterozygous PCSK1 variants affect BMI and obesity." (PMID 36292633, 2022). "The first report on the contribution of rare non-synonymous heterozygous PCSK1 variants to obesity dates from 2012." (PMID 36292633, 2022). "Three out of the eight previous rare heterozygous non-synonymous PCSK1 variants were detected, resulting in a combined 8.7-fold higher risk of obesity." (PMID 36292633, 2022). "To date, all PC1/3 deficiency cases carry either homozygous or compound heterozygous PCSK1 variants, and their carrier relatives only rarely suffer from obesity." (PMID 36292633, 2022). "Together with state-of-the art literature, this currently questions the involvement of rare heterozygous nonsynonymous PCSK1 variants in monogenic obesity and suggests a spectrum of effects on complex obesity depending on the remaining PC1/3 functionality." (PMID 36292633, 2022). "As a natural endogenous inhibitor of Pcsk1 (prohormone converting enzyme 1), Pcsk1n slows down the mediating effect of hormone converting enzyme and promotes food intake and obesity, and Pcsk1 gene mutations are common in the obese human population." (PMID 35525962, 2022). "The expression of Pcsk1(encoding proprotein convertase subtilisin/kexin type 1, which has been identified in patients with early-onset obesity) increased in alpha cells with a long-term HFHF diet." (PMID 35683981, 2022).
Obesity (continued). "Loss-of-function mutations of Pcsk1, Cnr1, and Bbs10 contribute to the development of obesity-associated features including severe early-onset obesity, increased waist circumference and skin-fold thickness, and higher adiposity." (PMID 36284088, 2022). "Loss-of-function mutations in PCSK1 cause a recessive complex endocrinopathy characterized by malabsorptive diarrhea and early-onset obesity." (PMID 34068683, 2021). "The first patient carrying compound heterozygous variants of PCSK1 gene showing postnatal malabsorptive diarrhea and early-onset obesity was reported in 1997." (PMID 34025722, 2021). "DNA, although itself unmodifiable, operates through modifiable pathways, e.g., the proprotein convertase subtilisin/kexin type 1 (PCSK1) gene regulates insulin synthesis; fat mass- and obesity-associated (FTO) gene promotes food intake." (PMID 33235315, 2021). "Haploinsufficiency has also been postulated in heterozygous mutations in partial prohormone convertase 1 (PCSK1) leading to obesity." (PMID 34448070, 2021). "Single-nucleotide polymorphisms in genome wide association studies have linked the PCSK1 locus with obesity demonstrating a role for the locus in susceptibility to commonly occurring obesity in the population and with fasting proinsulin." (PMID 31974728, 2020). "Patients with recessive mutations in PCSK1 exhibit a complex spectrum of traits including obesity, diarrhoea and endocrine disorders." (PMID 31974728, 2020). "Many genome studies of a variety of different populations have demonstrated a link between three frequent PCSK1 polymorphisms and an increased risk of obesity." (PMID 33261141, 2020). "Mutations on PCSK1 lead to a misprocessing of melanocortin peptides, then leading to obesity and abnormalities of glucose homeostasis and adrenal function." (PMID 32982666, 2020). "Proprotein convertase subtilisine/kexin type 1 (PCSK1), which encodes 1/3 prohormone convertase (PC 1/3), was one of the first genes linked to early-onset monogenic obesity." (PMID 33261141, 2020). "This is the second Pcsk1 mouse model to display obesity phenotypes, contrasting knockout mouse alleles." (PMID 31974728, 2020). "We describe here a new mouse model with a point mutation in the Pcsk1 gene that exhibits obesity, hyperphagia, transient diarrhoea and hyperproinsulinaemia, phenotypes consistent with human patient traits." (PMID 31974728, 2020). "On this point, it is important to note that clinical experience in the management of obesity in subjects with PWS is more profuse than in patients with PCSK1 deficiency, given the low number of patients with the latter." (PMID 29880780, 2018). "PCSK1 is mainly implicated in obesity, but promoter hypermethylation has been reported in cancer, mainly in malignant melanoma." (PMID 26497854, 2015). "In human studies, three patients with recessive monogenic form of obesity were deficient in the pro-protein convertase subtilisin/kexin type 1 (PCSK1) gene." (PMID 25825681, 2015). "Proprotein/neuroendocrine convertase deficiency, caused by rare mutations in PCSK1 gene, has been associated with obesity, severe malabsorptive diarrhea, and certain endocrine abnormalities." (PMID 25254043, 2014). "A study on association of PCSK1 rs6234 with obesity and related traits in Chinese population found that allele G was associated with increased beta-cell function estimated by HOMA-S and HOMA-B." (PMID 24489861, 2014). "Three BMI-increasing alleles of SNPs in or near TMEM18 and PCSK1 were nominally associated with increased risk of obesity (OR was 1.45 and 1.23, P = 0.002 on a binomial test)." (PMID 24626232, 2014). "A second study reported several common variants in PCSK1 associated with obesity in 1,094 Chinese individuals." (PMID 23451278, 2013). "Nevertheless, there is mixed evidence for the association of the rs6232, rs6234 and rs6235 PCSK1 variants with overweight, obesity and body mass index (BMI)." (PMID 23451278, 2013).
Obesity (continued). "To date, the role of common variants in PCSK1 in obesity is still unexplored in American population." (PMID 23451278, 2013). "PCSK1 polymorphisms association with obesity incidence during a 20-year follow-up of the CARDIA study." (PMID 23451278, 2013). "Rare PCSK1 variants causing total or partial PC1/3 deficiency have been reported to be associated with extreme obesity." (PMID 23451278, 2013). "Further replication studies are essential to confirm the association between genetic variation in PCSK1 and obesity in multi-ethnic American population." (PMID 23451278, 2013). "The results of this study indicate that common PCSK1 variants, notably the rs6232 and rs6235 polymorphisms contribute modestly to obesity in multi-ethnic American population." (PMID 23451278, 2013). "Two functionally relevant SNPs, originally identified in different PCSK1 alleles of a female patient with childhood early onset obesity, are associated with abnormal glucose homeostasis, and elevated plasma proinsulin and POMC levels." (PMID 23964269, 2013). "Among the PCSK family, mutations causing partial deficiency in PCSK1 have been linked to obesity, and mutations in PCSK9 are associated with hypercholesterolemia and coronary heart disease." (PMID 23936445, 2013). "Individuals who are compound heterozygotes or are homozygous for rare severe deleterious mutations in PCSK1 suffer from multi-dimensional disease states, including small intestinal dysfunction, hyperphagia and obesity." (PMID 23383060, 2013). "Common PCSK1 variants (notably rs6232 and rs6235) have been shown to be associated with obesity in European, Asian and Mexican populations." (PMID 23451278, 2013). "Our study evaluates the contribution of common variants in PCSK1 to the risk of obesity in a large multi-ethnic American sample." (PMID 23451278, 2013). "The discovery of genes causing monogenic forms of obesity such as the prohormone convertase subtilisin/kexin type 1 gene (PCSK1) has greatly improved our understanding of the pathophysiology of obesity." (PMID 22737226, 2012). "Common variants rs6232 and rs6235 in the PCSK1 gene have been associated with obesity in European populations." (PMID 22737226, 2012). "To investigate the underlying phenotypes of obesity, we evaluated the effects of the G-allele of PCSK1 rs6232 and the C-allele of PCSK1 rs6235 in 6,039 treatment-naïve Danes on measures of obesity by applying an additive model adjusted for sex and age." (PMID 21935364, 2011). "Loss-of-function rare mutations in the PCSK1 gene have been associated with obesity both in humans and rodents." (PMID 22043164, 2011). "In the Danish study sample significant interaction was only seen between C-allele of PCSK1 rs6235 and sex for traits related to obesity." (PMID 21935364, 2011). "Association between measures of obesity stratified according to sex for the PCSK1 rs6235 among 5,788 treatment-naïve Danes." (PMID 21935364, 2011). "PCSK1 was suspected as an obesity risk gene in linkage studies identifying an obesity-region located on chromosome 5 including the PCSK1-locus." (PMID 21935364, 2011). "The present study evaluated the effects of the non-synonymous rs6232 G-allele and the rs6235 C-allele within PCSK1 on measures of obesity and glucose homeostasis in the fasting state, after an oral glucose load and following a meal test." (PMID 21935364, 2011). "Our study was underpowered to detect the previous reported associations of the PCSK1 variants with obesity." (PMID 20534142, 2010). "Further studies with larger sample sizes are warranted to confirm the association between common variants in PCSK1 and obesity risk in Chinese Hans, especially in women." (PMID 20498726, 2010). "Common variants in PCSK1 have been reported to be associated with obesity in populations of European origin." (PMID 20498726, 2010).